RIPK2 (receptor interacting serine/threonine kinase 2)
Diseases named in the same sentence as RIPK2 in open-access papers (continued):
Sharing a sentence is not in itself a finding about the gene and the disease.
ovarian carcinoma (5 papers, 2013 to 2026). A malignant neoplasm originating from the surface ovarian epithelium. "RIPK2 is highly expressed in paclitaxel-resistant ovarian cancer cell lines, and high RIPK2 expression is associated with paclitaxel resistance in plasmacytoid ovarian cancer." (PMID 41563982, 2026). "The correlation coefficient was 0.46 (p < 0.05), indicating that higher expression of RIPK2 was associated with Taxol resistance of multiple ovarian cancer cell lines." (PMID 35477477, 2022). "RIPK2 was highly expressed in Taxol resistant ovarian cancer cell lines, and its high expression was also linked with shorter OS and PFI in serous ovarian cancer patients." (PMID 35477477, 2022). "Therefore, our research suggests that ASAP1 mutation might be related to RIPK2 alteration and thus be associated with Taxol resistance in ovarian cancer." (PMID 35477477, 2022). "Recent studies have shown that RIPK2 mediates paclitaxel resistance in ovarian cancer and temozolomide resistance in glioma." (PMID 41563982, 2026). "NOD1/2 act as an oncogene in ovarian cancer by upregulating immune-related pathways such as the RIPK2/NFκB signaling pathway." (PMID 39149564, 2024). "Equally, NOD-1 protein was found to phosphorylate NF-κB by binding to the protein receptor that interacts with serine/threonine kinase 2 (RIPK2), enhancing the proliferative and invasive properties of ovarian cancer cell lines." (PMID 37624039, 2023). "In our study, RIPK2 alterations were found in 10% of ovarian cancer patients who were treated with Taxol." (PMID 35477477, 2022). "We also found that the copy number of OSGIN2, and NBN differed in RIPK2-altered and RIPK2-unaltered patients, and these genes were coexpressed with RIPK2 in ovarian cancer." (PMID 35477477, 2022). "This idea was confirmed when we found that the expression of RIPK2 was positively related to the IC50 of Taxol in multiple ovarian cancer cell lines using data from the CCLE database." (PMID 35477477, 2022). "The cBioPortal tool was used to determine the alterations in RIPK2 in ovarian cancer patients who were treated with Taxol in the TCGA-OV database." (PMID 35477477, 2022). "AMP was the most common type of RIPK2 copy number alteration (CNA) in ovarian cancer." (PMID 35477477, 2022). "In ovarian cancer, all of the up-regulated genes were increased with more advanced stage (CXCL10, RIPK2 and SPP1) or higher pathological grade (CXCL11, KPNA2, RSAD2, THOC4 and TNC)." (PMID 23536776, 2013). "ISG15, SNCA, RIPK2, PLCG2, RHOU, TRIB2 and ELP2 influenced the OS and PFI of ovarian cancer patients in the TCGA-OV dataset, while RIPK2 also affected the OS and PFI of ovarian cancer patients treated with Taxol in the GSE30161, GSE32062 and GSE63885 datasets." (PMID 35477477, 2022).
asthma (4 papers, 2022 to 2023). "Furthermore, the histological analysis of the RIPK2 deficient mice lungs showed an improvement of the classic lung pathology features of asthma." (PMID 36189256, 2022). "In accordance with these results, our group has shown that both NOD1 deficient and RIPK2 deficient mice, when subjected to an HDM asthma protocol, present reduced asthma features including reduced AHR, eosinophil, and neutrophil recruitment." (PMID 36189256, 2022). "have explored the use of one of these promising RIPK2 inhibitors in an HDM experimental asthma model with relative success." (PMID 36189256, 2022). "In contrast, NOD1, as well as RIPK2 adaptor deficiency, strongly downregulated all the features of HDM-induced asthma." (PMID 36233196, 2022). "The relevant role of NOD1 and NOD2 not only in asthma but also in other diseases with an inflammatory component, such as Crohn ́s disease, has encouraged the development of different compounds with the ability to target their signaling pathways, mainly the adaptor protein RIPK2." (PMID 36189256, 2022). "The administration of the selective GSK583 RIPK2 inhibitor via the mice diet prior to and during the HDM sensitization phase of an acute asthma model resulted in a reduction of the eosinophilia, neutrophilia, and histopathology features of the asthmatic mouse." (PMID 36189256, 2022). "RIPK2 is the downstream adaptive protein in both the NOD1 and NOD2 signaling pathways, and as such, is a critical mediator in the NOD1 and NOD2-related implication in asthma development." (PMID 36189256, 2022).
Blau syndrome (4 papers, 2015 to 2023). Blau syndrome (BS) is a rare systemic inflammatory disease characterized by early onset granulomatous arthritis, uveitis and skin rash. "RIPK2 is one emerging therapeutic target in inflammation strongly supported by genetic evidence of activating NOD2 mutations in the monogenic autoinflammatory disease Blau syndrome, characterized by early-onset granulomatous arthritis, uveitis, and dermatitis." (PMID 26320862, 2015).
Insulin resistance (4 papers, 2017 to 2024). Increased resistance towards insulin, that is, diminished effectiveness of insulin in reducing blood glucose levels. "Moreover, administration of gefitinib, a RIPK2 inhibitor, attenuated metabolic inflammation and insulin resistance caused by NOD1 activation." (PMID 36268029, 2022). "Because of the recognized contributions of dyslipidemia and inflammation to insulin resistance, we sought to test if TKI-mediated inhibition of RIPK2 could attenuate NOD1-induced impairments in insulin signalling in adipocytes." (PMID 28484277, 2017). "Furthermore, a bone marrow transplantation experiment revealed that non-hematopoietic expression of RIPK2 is required for the NOD2-mediated protection against insulin resistance and metabolic syndrome." (PMID 36268029, 2022).
multiple sclerosis (4 papers, 2018 to 2023). A progressive autoimmune disorder affecting the central nervous system resulting in demyelination. "Further proving its role in neuroinflammatory processes, mice globally deficient for the Ripk2 allele (Ripk2−/−) were protected from experimental autoimmune encephalomyelitis, a rodent model of multiple sclerosis." (PMID 37777791, 2023). "Ripk2 has been implicated in the caspase-1 pathway of hypoxia and ischemia-induced neuronal cell death, as well as the pathology of neuroinflammatory diseases such as multiple sclerosis." (PMID 35743792, 2022). "RIPK2 also participates in the activation of CNS-infiltrating dendritic cells and is involved in the progression of multiple sclerosis (MS), a progressive neuroinflammatory disorder." (PMID 36959850, 2023).
sarcoidosis (4 papers, 2018 to 2023). Sarcoidosis is a multisystemic disorder of unknown cause characterized by the formation of immune granulomas in involved organs. "However, excessive NOD2 signaling has been associated with various diseases, including sarcoidosis and inflammatory arthritis; the pharmacological inhibition of RIPK2 is an affinity strategy that demonstrates an increased expression of pro-inflammatory secretion activity." (PMID 29463017, 2018). "In alveolar macrophages (AMs) and peripheral blood mononuclear cells (PBMCs) isolated from patients with sarcoidosis, RIPK2 expression was substantially higher compared to the controls." (PMID 36959850, 2023). "Pretreating Pam3CysSK4–TLR2 ligand (PAM) stimulated sarcoidosis AMs or PBMCs with a combination of IL-1 receptor-associated kinase (IRAK) 1/4 inhibitor and gefitinib (a non-selective RIPK2 inhibitor, vide infra) led to the reduction of IL-1β, IL-6 and INF-α productions." (PMID 36959850, 2023).
Stroke (4 papers, 2023 to 2025). Sudden impairment of blood flow to a part of the brain due to occlusion or rupture of an artery to the brain. "To assess the effect of Ripk2 deletion on infarct size after stroke, we first induced 45 min-transient middle cerebral artery occlusion (tMCAO) in mice sufficient (Ripk2+/+) and deficient (Ripk2−/−) for the Ripk2 gene and sacrificed the mice 24 h later." (PMID 37777791, 2023). "As such, we next generated mice deficient for Ripk2 in microglia using the Cre-lox system under the control of the Tmem119 promoter and subjected them to stroke." (PMID 37777791, 2023). "As such, we wanted to assess the transcriptional response of microglia derived from Ripk2 globally deficient mice after stroke." (PMID 37777791, 2023). "Mice deficient in RIPK2 exhibited a reduced inflammatory response and neuronal apoptosis, with a smaller infarct volume and improved neurological deficits score, while neuron-specific RIPK2 overexpressing transgenic mice displayed worse stroke outcomes than wild-type (WT) controls." (PMID 39519307, 2024). "This study is significant because it uses aged animals, an important consideration for experimental stroke research, to investigate the effects of RIPK2 on infarct volume and behavioral outcomes post-stroke." (PMID 40225421, 2025). "In the current study, we utilized a genetic approach to assess the role of RIPK2 in neuroinflammation following the pMCAO model of stroke in aged mice." (PMID 40225421, 2025). "This is further illustrated by our open field test data, as the Ripk2-/- mice spent less time in the center of the arena than the WT controls both at baseline and following stroke." (PMID 40225421, 2025). "This study further elucidates the role of RIPK2 signaling in the ischemic cascade and expands our knowledge of RIPK2 in stroke to aged mice." (PMID 40225421, 2025). "When normalized to baseline data, aged Ripk2-/- mice were able to descend the vertical grid more quickly and hold more weight than aged WT controls after stroke." (PMID 40225421, 2025). "Receptor-interacting serine/threonine kinase 2 (RIPK2) is an important mediator in the post-stroke inflammatory cascade that responds to signals and molecular patterns released by dead or dying cells in the ischemic area." (PMID 40225421, 2025). "Previous studies in our lab have explored the role of RIPK2 in post-stroke neuroinflammation mechanistically by using genetic models and pharmacological inhibitors of RIPK2 in young animals." (PMID 40225421, 2025). "This study aims to expand the data showing the role of RIPK2 signaling in stroke by using aged global Ripk2 knockout mice and assessing long-term motor and cognitive behavior, as well as infarct size and gliosis measurements." (PMID 40225421, 2025). "We have also shown in young mice that pharmacologically inhibiting RIPK2 following stroke is neuroprotective, reduces infarct volume, and improves behavioral outcomes in acute studies." (PMID 40225421, 2025). "Our results show that RIPK2 plays an important role in the post-stroke pathology that worsens infarct size and behavioral outcomes." (PMID 40225421, 2025). "We utilized the pMCAO model and examined the effects of Ripk2-/- on behavior outcomes, infarct volume, and microglial/macrophage and astrocytic activation at 28 days post-stroke." (PMID 40225421, 2025). "Treatment with a RIPK2 inhibitor at the onset of reperfusion after MCAO attenuated the RIPK2 phosphorylation induced by stroke and significantly reduced infarct volume and blood–brain barrier (BBB) disruption." (PMID 39519307, 2024). "We also observed a significant number of RIPK2+, Iba1+ double-positive cells in the ipsilateral cortex after stroke." (PMID 37777791, 2023). "Using the weight grip test, we found that Ripk2−/− animals also displayed greater preservation of grip strength after stroke, as evidenced by their improved grip scores." (PMID 37777791, 2023).
Stroke (continued). "In our μKO studies, we showed that microglia utilize RIPK2 to promote stroke injury and that deleting the Ripk2 gene specifically in microglia results in decreased infarct size and reduced markers of BBB disruption." (PMID 37777791, 2023). "RT-qPCR of the ipsilateral cerebral cortex (CXI) revealed that Ripk2−/− mice have a dramatically lower classical markers of neuroinflammation in the brain after stroke compared to their Ripk2+/+ counterparts." (PMID 37777791, 2023). "Global genetic deletion of Ripk2 resulted in decreased infarct sizes and reduced neuroinflammatory markers 24 h after stroke compared to wild-type controls." (PMID 37777791, 2023). "We found that aged male Ripk2−/− mice subjected to pMCAO displayed less brain injury at 48 h after stroke as detected by TTC staining compared to aged-matched WT controls." (PMID 37777791, 2023). "This study identifies RIPK2 as a potent propagator of neuroinflammatory signaling, highlighting its potential as a therapeutic target for post-stroke intervention." (PMID 37777791, 2023). "We created a paradigm, where microglia are rendered genetically incapable of propagating RIPK2 signaling to explore the RIPK2–microglial contribution to stroke injury." (PMID 37777791, 2023). "We determined that RIPK2 is highly expressed in Iba1-positive cells in the ipsilateral cortex after stroke." (PMID 37777791, 2023). "We provide new evidence that RIPK2 plays a pathological role in the progression of stroke injury by promoting neuroinflammation and increasing infarct size in both the acute and late stages of injury." (PMID 37777791, 2023). "Ripk2−/− mice displayed a greater ability to descend the vertical grid at nearly all testing timepoints after stroke." (PMID 37777791, 2023). "In our study, we sought to mechanistically investigate the role of RIPK2 in the progression of stroke injury by studying the effects of stroke in Ripk2−/− mice as well as in mice with microglia-specific deletion of Ripk2 (termed μKO)." (PMID 37777791, 2023). "Surprisingly, we found that global deletion of Ripk2 resulted in zero mortality out to 28-day post-stroke, whereas WT animals suffered 50% mortality." (PMID 37777791, 2023). "We induced pMCAO in aged male and female wild type (WT) and Ripk2−/− mice and evaluated their anatomical outcomes after stroke." (PMID 37777791, 2023). "Repurposing currently available RIPK2 inhibitors/degraders for post-stroke therapy offers an exciting novel strategy for targeted treatment." (PMID 37777791, 2023). "To add greater translational relevance to the protective role of Ripk2 deletion in stroke, we wanted to know how these animals would perform with both the comorbidity of age and a permanent occlusion model of stroke." (PMID 37777791, 2023). "Analysis of 770 neuroinflammation-associated genes in the ipsilesional cortex of our μKO and WT control mice 48 h after stroke revealed insights into potential mechanisms of protection in mice, where Ripk2 is specifically deleted from microglia." (PMID 37777791, 2023). "Post-stroke cognitive impairment is a common post-stroke outcome, and interventions that reduce post-stroke neurological deficits, such as what we observed with Ripk2 global deletion, are greatly needed." (PMID 37777791, 2023). "We will further investigate the contribution of peripheral immune cell usage of RIPK2 by inducing stroke in animals, where Ripk2 is specifically deleted from myeloid-derived immune cells." (PMID 37777791, 2023). "To determine the effects of microglial Ripk2 deletion on post-stroke behavioral outcomes, we subjected μKO mice and WT controls to a battery of behavioral tests during the acute 48 h phase of injury." (PMID 37777791, 2023). "Ripk2−/− mice had decreased levels of Iba1+ cells in the ipsilateral cortex 6 h after stroke compared to the Ripk2+/+ mice, implicating a diminished microglia response to injury." (PMID 37777791, 2023).
Stroke (continued). "Additionally, future studies should use pharmacological inhibitors of RIPK2 long-term following stroke to further investigate the therapeutic potential of RIPK2 inhibition to reduce inflammation and improve outcomes following ischemic stroke." (PMID 40225421, 2025). "We hypothesize that RIPK2 signaling worsens injury and neurological recovery post-stroke and that global deletion of Ripk2 is protective following ischemic stroke in aged mice." (PMID 40225421, 2025). "Additionally, aged WT mice have increased expression of Iba1 in the ipsilateral cortex compared to aged Ripk2-/- mice, potentially showing a negative regulation role of RIPK2 in microglial/macrophage activation following stroke." (PMID 40225421, 2025). "Stroke-induced RIPK2 upregulation and its potential brain-gut axis interactions suggest that RIPK2 inhibition may alleviate acute neural injury by modulating microglial responses." (PMID 40406369, 2025). "Additionally, we opted to do a longitudinal study in the aged Ripk2-/- mice to assess long-term recovery and cognitive function following stroke." (PMID 40225421, 2025). "This study utilized aged Ripk2-/- mice to assess the role of RIPK2 post-stroke at advanced age." (PMID 40225421, 2025). "Behaviorally, μKO mice retained better motor function when assessed across the various behavioral paradigms compared to WT mice during the acute 48 h period of stroke injury, implicating that microglia play a specific role in propagating stroke-induced behavioral deficits through RIPK2." (PMID 37777791, 2023). "We also performed bulk RNA-sequencing of microglia isolated from WT and Ripk2−/− mice after stroke." (PMID 37777791, 2023). "We also found that Ripk2 knockout mice had greater preservation of tight junction proteins Zona occludens-1 (ZO-1) and Occludin in the ipsilateral cortex 24 h after stroke, which was concurrent with lower levels of active-MMP-9, a major contributor to BBB opening." (PMID 37777791, 2023). "Ripk2 global deletion also improved both acute and long-term behavioral outcomes with powerful effects on reducing infarct volume and mortality at 28d post-stroke." (PMID 37777791, 2023). "Pharmacological inhibition or degradation of RIPK2 in vivo may also prove beneficial in improving stroke outcomes." (PMID 37777791, 2023). "We next sought to determine the long-term effects of Ripk2 deletion in animals after stroke." (PMID 37777791, 2023). "Importantly, we conducted a longitudinal study and showed that Ripk2−/− mice have reduced infarct volumes and zero mortality out to 28-day post-stroke compared to Ripk2+/+ mice." (PMID 37777791, 2023). "As neuroinflammatory processes contribute to the expansion of stroke injury in the acute phase, we next determined that the Ripk2 KO mice displayed robust decreases in neuroinflammatory gene transcription concurrent with indicators of greater BBB preservation compared to their WT counterparts." (PMID 37777791, 2023). "We have also shown that both global knockout and microglia-specific conditional knockout of Ripk2 results in smaller infarct volumes and improved behavioral outcomes, implicating the microglia as a primary driver of the detrimental effects of RIPK2 signaling post-stroke." (PMID 40225421, 2025). "We speculate that there may be a greater role for RIPK2 utilization by peripheral immune cells, who are known to express RIPK2, in promoting stroke injury, and that this may explain the more powerful protective effect observed in our Ripk2−/− compared to our μKO animals." (PMID 37777791, 2023). "Finally, bulk transcriptomic profiling and nanoString data demonstrated that Ripk2 deficiency in microglia decreases genes associated with MAPK and NF-κB signaling, dampening the neuroinflammatory response after stroke injury by reducing immune cell activation and peripheral immune cell invasion." (PMID 37777791, 2023).